INS (insulin)
Diseases named in the same sentence as INS in open-access papers (continued):
Sharing a sentence is not in itself a finding about the gene and the disease.
diabetes (continued). "The retrospective evidence available is more controversial, with studies showing either no mortality differences in comparison to HF patients with diabetes treated with oral antidiabetic agents, or increased mortality in insulin‐requiring patients." (PMID 33463901, 2021). "An experimental animal model of diabetes revealed that neutralization of SELENOP improved glucose tolerance and insulin secretion, suggesting that this selenoprotein may play a particularly important role in the pathogenesis of T2DM." (PMID 34262926, 2021). "In addition, hybrid insulin peptides were suggested to be processed in the β cell crinophagic bodies (crinosomes), where insulin degradation products are fused and then presented by MHC class II molecules, leading to diabetes and autoimmunity." (PMID 34022431, 2021). "Subjects without diabetes were grouped based on insulin sensitivity (Si) measured during the frequently sampled, insulin-modified, intravenous glucose tolerance test (FS-IVGTT), and the groups were matched for sex and age." (PMID 34369385, 2021). "For example, over 40% of adolescents with diabetes do not carry out scheduled blood glucose monitoring and over 25% miss at least one insulin injection per week." (PMID 38774890, 2021). "We first looked at mRNA levels of common cytokines in diabetes under high levels of glucose with and without insulin." (PMID 33135334, 2021). "Type 1 diabetes mellitus (T1DM) is a chronic disease due to lack of insulin hormone production from pancreatic β-cells." (PMID 33639953, 2021). "In the case of patient experiencing diabetes with a high glucose level, such as 400 mg/dL, it is required to regulate it with medication or insulin to reduce the chance of long-term negative health effects." (PMID 33804904, 2021). "Diabetes is defined as a lack of insulin action with systemic consequences, including hyperglycemia, ketonuria and acidosis." (PMID 33923498, 2021). "In type 1 diabetes, pancreatic β-cells do not synthesize insulin or synthesize an insufficient amount, patients are treated with insulin, and therefore this type of diabetes is also known as insulin-dependent diabetes mellitus (IDDM)." (PMID 34833990, 2021). "Our data suggest that high insulin requirements observed in patients with severe COVID‐19 are related to the severity of respiratory failure and pre‐existing diabetes mellitus rather than a direct diabetogenic effect of SARS‐CoV‐2." (PMID 34268452, 2021). "The patient had a history of poorly controlled type 1 diabetes mellitus and had been non-adherent to her insulin regimen." (PMID 37465067, 2021). "Together these results indicate that insulin is an inhibitor of FGF23, at least partially independent of the inflammation associated with diabetes." (PMID 33716961, 2021). "In previous studies, African Americans without diabetes and black African men with early diabetes exhibited lower insulin secretion compared with their White counterparts for their given insulin sensitivity for glucose metabolism." (PMID 34879878, 2021). "In terms of medical treatment for diabetes, 76% (196/258) used oral medication, 84.1% (217/258) injected insulin, 3.9% (10/258) had other treatment, and 3.5% (9/258) had no treatment." (PMID 34328429, 2021). "The Baltimore Eyes Study reported increased mean IOP in patients using insulin compared to those without diabetes." (PMID 34521935, 2021). "Studies including participants with variable experience in diabetes technology use (on multiple daily insulin injections and without previous sensor use) and from more diverse socioeconomic backgrounds are important to support generalisability of benefits." (PMID 33550442, 2021). "It is well known that exercise reduces body fat mass and systemic inflammation as well as improves insulin sensitivity and glycemic control thus it is not surprising that people who participate in more leisure-time PA are less likely to develop diabetes." (PMID 34158561, 2021).
diabetes (continued). "Different D-Chiro-Ins dosages can be eventually conceived (and properly tested) in specific pathological conditions (anti-estrogenic treatments, diabetes)?, with the aim to primarily inhibit aromatase activity or foster insulin activity in non-ovarian tissues." (PMID 33889133, 2021). "Contrary to current guidelines, the patient’s diabetes was managed exclusively with short-acting insulin which was administered as needed without basal insulin." (PMID 33581735, 2021). "In fact, both the Med diet and LC diet produced a greater increase in surrogate markers of β-cell function, compared with the respective control diets, in insulin-resistant subjects without diabetes." (PMID 33919503, 2021). "A detailed characterization of insulin signaling pathways under metabolic stress following UCN3 overexpression is planned, and the results are expected to further elucidate the action of UCN3 on adipocytes in the context of obesity and diabetes." (PMID 34341463, 2021). "When pancreatic insulin secretion is no longer sufficient to compensate for insulin resistance, glucose intolerance progresses to chronic hyperglycemia and overt diabetes." (PMID 34439505, 2021). "One cross-sectional study of participants without diabetes demonstrated that the insulin sensitivity index significantly correlated with WC across populations." (PMID 33931084, 2021). "Additional analyses comparing users of DPP-4 inhibitors with subgroups of non-users (subgroup 1: users of metformin and sulphonylurea; subgroup 2: users of any insulin combination), allowing to correct for diabetes severity, did not yield different results." (PMID 34222054, 2021). "Remarkably, in the present study, we did not observe an increase in chemerin in patients with diabetes mellitus, probably because we did not include patients with uncontrolled diabetes or patients receiving insulin." (PMID 34506500, 2021). "SMBG has been shown to improve glycemic control among diabetes patients using insulin, although its value for those with non-insulin-treated T2DM has remained inclusive." (PMID 33717708, 2021). "Nowadays, diabetes’ is the main health concern especially type 2 diabetes mellitus (T2DM) remains a terrible metabolic disorder across the world categorized by hyperglycemia, due to the abnormal regulation of insulin." (PMID 34946757, 2021). "Diabetes is a chronic metabolic disorder that is illustrated by either insufficient production or the lack of response to insulin, a key hormone in the regulation of the body’s metabolism." (PMID 33918509, 2021). "We further determined that retinal insulin protein content did not vary with overnight fasting or diabetes." (PMID 33915127, 2021). "Amongst women receiving insulin prior to ANC, those with gestational diabetes were receiving the smallest dose and women with type 2 diabetes the largest dose, but the percentage increase in dose after ANC was approximately 80% for all types of diabetes." (PMID 33600450, 2021). "On the other hand, linagliptin, empagliflozin and combination therapy did not alter serum insulin and glucagon levels in both an early and advanced phase of diabetes." (PMID 34373487, 2021). "The HI-5 study was the first RCT of intensive insulin infusion that included hyperglycaemic ACS patients without previously established diabetes." (PMID 33466656, 2021). "In the NASH-STZ hamster we do not expect hyperinsulinemia to be a contributing factor, due to the method of diabetes induction (low-dose STZ), however, because of the prolonged hyperglycemia we do expect the NASH-STZ hamster to be insulin resistant as a consequence of glucose toxicity." (PMID 33596938, 2021). "The mean ±SD duration of diabetes was 4.64 ±3.31 years, and 95% of participants were on MDI insulin therapy consisting of four injections including one injection of long-acting insulin in the evening and an injection of rapid-acting insulin before each meal per day." (PMID 36511230, 2021).
diabetes (continued). "However, LDAT significantly decreased LDL level and increased insulin and HOMA-β levels compared to diabetes control group (p < 0.05)." (PMID 33641315, 2021). "In 2019, we found a podiatrist consultation in 3.7% of patients with treated diabetes with 2.5 times more among insulin-treated patients (6.2%) versus non-insulin-treated (2.4%)." (PMID 34917037, 2021). "Patterns of insulin secretion in diabetes patients have been shown to be more irregular and not closely linked to glucose responses." (PMID 33658478, 2021). "We also found that being the spouse of a patient with diabetes was an independent determinant of low insulin sensitivity, independent of the BMI." (PMID 34442147, 2021). "We first investigated various candidate antigens, including insulin, insulinoma antigen-2 (IA-2), and glutamic acid decarboxylase (GAD), that had been previously identified as autoantibody targets in diabetes but found that extracts and/or peptides of these proteins did not activate BDC T cells." (PMID 33673706, 2021). "In the case of diabetes and diabetes-related complications, biotin-fabricated nano-liposomes were found to be effective for the oral administration of insulin without leakage and also facilitated the uptake of insulin via receptor-mediated endocytosis." (PMID 35223819, 2021). "Trials involving women with diabetes in pregnancy either did not report gastrointestinal side effects in the insulin arm, or reported zero values." (PMID 33927270, 2021). "On the other hand, a severe COVID-19 infection, and its treatment with steroids, can have a specific negative impact on diabetes itself, leading to worsening of hyperglycemia through increased insulin resistance and reduced β-cell secretory function." (PMID 34220706, 2021). "Diabetes mellitus (DM) is a chronic disease that occurs as the result of the reduction of insulin hormone in the body or when the body itself is not able to utilise the insulin effectively." (PMID 34068490, 2021). "Most people with diabetes at primary care level are treated without insulin therapy, even often with no antidiabetic drug." (PMID 33836823, 2021). "We analyzed insulin-treated diabetes mellitus, non-insulin-treated diabetes mellitus, and patients without diabetes mellitus." (PMID 33225841, 2021). "The huge advances in molecular biological and neuroscience tools over the past 30 years have opened the way for a greater understanding of how the brain, a non-classical insulin-sensitive tissue, is impacted by diabetes." (PMID 33845179, 2021). "Since excessive generation of IL-6 and TNF-α compromise insulin sensitivity, suppression of IL-6 and TNF-α by carnosine and histidine can have beneficial effects on reducing or preventing diabetes-related complications as well as preventing altered endothelial function by inflammation." (PMID 34203479, 2021). "Participants were matched based on their use of insulin or not and their diabetes goals or problems." (PMID 33604060, 2021). "Thirty adults aged ≥60 years with insulin-treated diabetes mellitus (type 1 or 2), and 30 without, all with mild frailty (3–4 on the Rockwood Frailty Scale) will be recruited." (PMID 34880011, 2021). "While studies assessing the correlation between leptin and diabetes mellitus are sparse, a predictive role of circulating serum leptin on reducing insulin sensitivity over time was observed in nondiabetic men." (PMID 34299261, 2021). "Diabetes Mellitus (DM), with an estimated worldwide prevalence of 285 million patients, is an increasingly prevalent metabolic disorder that is characterized by persistent hyperglycemia caused by insulin resistance or a lack of insulin." (PMID 33806202, 2021). "However, when β-cells are chronically exposed to hyperglycemia in type 2 diabetes mellitus (T2DM), insulin biosynthesis and secretion are decreased together with reduced expression of insulin transcription factors." (PMID 34360682, 2021).
diabetes (continued). "The likelihood of pre-eclampsia was non-significantly reduced in women with diabetes in pregnancy randomised to metformin versus insulin." (PMID 33927270, 2021). "This is a case presentation of a 15-year-old female with type 1 diabetes mellitus who was not fully adherent to her insulin regimen and presented in acute diabetic ketoacidosis." (PMID 37465067, 2021). "It should be noted that remission was higher among patients with recent onset of diabetes and those who were not taking insulin." (PMID 33893610, 2021). "Based on the temporal effects on insulin secretion in the present study and our previous finding that long-term ALT administration reduced diabetes incidence in NOD mice, we hypothesized that local immunopathology within the pancreas may be altered." (PMID 34203471, 2021). "In diabetics, CGMS was connected to an insulin pump for precise glucose control." (PMID 34362176, 2021). "Type 2 diabetes mellitus (T2DM), in contrast, is characterized by a relative scarcity of insulin, which manifests as IR, a state in which essential organs, such as the liver and muscles, are less sensitive to insulin." (PMID 34906241, 2021). "All these effects most likely contribute to the impaired expression and function of proteins involved in appropriate β-cell function and in the lack of compensation for a higher insulin demand under obese conditions during diabetes development." (PMID 34445304, 2021). "α-HB acid has been shown to be the top-ranked candidate to separate insulin-resistant from insulin-sensitive individuals in biochemical profiling studies in subjects without diabetes." (PMID 34684324, 2021). "Findings reveal that the majority of people with diabetes were found non-compliant with physical activity and insulin use." (PMID 34826318, 2021). "Both hypothyroidism and hyperthyroidism are able to influence the metabolism of insulin and thus induce insulin resistance, suggesting a non-linear, possible U-shaped, relationship between thyroid function and diabetes." (PMID 34670571, 2021). "Ultimately, the goal of islet transplantation research using the omentum site is to restore insulin production in diabetes patients without the need for immunosuppressive drugs." (PMID 34589059, 2021). "Hyperinsulinemic persons tend to have an insulinotropic effect by smoking and chronic smokers with or without diabetes have a significantly reduced insulin sensitivity which in turn led to hyperinsulinemia." (PMID 34746266, 2021). "Diabetes is classified as insulin-dependent type I and insulin-non-dependent type II, and approximately 95% of patients with diabetes are diagnosed with type II diabetes." (PMID 34684383, 2021). "Reductions in visceral fat have been shown to improve glucose tolerance and insulin sensitivity in those with and without diabetes." (PMID 34409961, 2021). "Protein tyrosine phosphatase 1B (PTP1B) is a critical negative modulator of insulin signaling and has attracted considerable attention in treating type 2 diabetes mellitus (T2DM)." (PMID 34884501, 2021). "The authors concluded that retinal synapses were lost within 1 month of uncontrolled diabetes and suggest that synapses are not regained with glycemic control and restoration of insulin signaling." (PMID 34944588, 2021). "In the Russian Federation, approximately 8.1 million people suffer from diabetes, and insulin non-dependent form or type 2 diabetes is responsible for a majority of these cases." (PMID 34575035, 2021). "In the univariate analyses, fasting plasma glucose (FPG), fasting serum insulin (FINS), 2 h plasma glucose (2hPG), HbA1c, serum uric acid (SUA), waist circumference (WC), smoking, and family history of diabetes (FHD) were found to be significantly correlated with prediabetes." (PMID 34804156, 2021). "No significant delay in diabetes onset was observed overall between 7.5 mg/d oral insulin and placebo groups." (PMID 33418839, 2021).
diabetes (continued). "Currently, AI technologies that mimic the “hidden tips of treatments by a specialist,” such as fine-tuning insulin dose, are being developed rather than just a support system for diabetes diagnosis itself." (PMID 34902070, 2021). "Hence, the critical role of HIF1 in establishing the diabetes-cancer link needs to be fully elucidated by probing into the intricate crosstalk between HIF1 and insulin signaling." (PMID 34225729, 2021). "Also, leptin and HOMA-IR levels increased, while insulin and HOMA-β levels decreased in the diabetes control group." (PMID 33641315, 2021). "AP3B1 is known to have variants associated with fasting insulin and HOMA-IR in African Americans without diabetes." (PMID 34863089, 2021). "Type 2 diabetes mellitus (T2DM) is the most frequent type of diabetes which can develop metabolic syndrome due to the basic dysfunctions of insulin (resistance or lack of secretion)." (PMID 34394276, 2021). "In diabetes mellitus, the feedback loops between insulin action and insulin secretion do not function properly." (PMID 34073816, 2021). "Diabetes is characterized by increased blood glucose due to insufficient or lack of insulin production, or inability of peripheral tissues to respond to insulin (insulin resistance, IR)." (PMID 34631209, 2021). "In this exploratory study, we begin to evaluate the hypothesis that Microburst Insulin Infusion (MII) may be efficacious in treating HbA1c and complications of diabetes." (PMID 34458216, 2021). "The relationship between gram-negative organisms and diabetes is further substantiated by the reduction in insulin sensitivity following vancomycin administration, which resulted in a marked reduction in butyrate-producing organisms." (PMID 34001264, 2021). "Those who experienced hypoglycaemia had longer duration diabetes and were thus mostly treated with insulin rather than the newer oral or injectable blood glucose-lowering therapies that are associated with a low rate of this acute metabolic complication." (PMID 34790048, 2021). "Diabetes, a chronic disease, occurs when the pancreas is no longer able to make insulin or when the body cannot make fair use of the insulin it produces." (PMID 33825598, 2021). "A recent known molecular target to treat diabetes is PTP1B which plays a significant role in the negative feedback of insulin signaling." (PMID 34093192, 2021). "Since insulin treatment is relatively common in type 2 diabetes, it would not be appropriate to classify the type of diabetes based on the use of insulin alone." (PMID 34836302, 2021). "Metformin was the most prevalent diabetes drug (60.9 and 59.1% in AD- and non-AD cohorts, respectively) followed by sulfonylureas and insulin." (PMID 34911481, 2021). "Diabetes mellitus (DM) is a chronic metabolic disease characterized by elevated blood glucose levels, due to the lack of insulin production, the resistance to insulin signaling or both." (PMID 34260684, 2021). "The SGLT2 inhibitors reduce glucose reabsorption through renal systems, thus improving glycemic control in all stages of diabetes mellitus, independent of insulin." (PMID 34281221, 2021). "At the centenary of the discovery of insulin, the medical and scientific communities pause to reflect on what the pancreatic hormone has meant not just for people with diabetes but indeed for medicine and science in general." (PMID 35602193, 2021). "Insulin pump therapy, or continuous subcutaneous insulin infusion (CSII), has been in use since the 1970’s and aims to mimic physiological insulin delivery for people with diabetes." (PMID 33950566, 2021). "Hyperglycemia is a main characteristic of diabetes largely due to either the lack of insulin secretion or impaired insulin signaling (i.e., insulin resistance)." (PMID 34831481, 2021). "2.5 x106 murine CD4+ Insulin-CAR-FOXP3-T cells failed to prevent the onset of diabetes in prediabetic NOD mice." (PMID 33854514, 2021).